KCNQ1 (potassium voltage-gated channel subfamily Q member 1)
Diseases named in the same sentence as KCNQ1 in open-access papers (continued):
Sharing a sentence is not in itself a finding about the gene and the disease.
Iron-deficiency anaemia (3 papers, 2014 to 2023). "Interestingly, impaired function of KCNQ1 results in iron-deficient anemia in Jervell and Lange-Nielsen syndrome patients." (PMID 25127743, 2014). "Moreover, KCNQ1 protein was found to express in inner ear regions and the gastrointestinal tract, giving explanations for the defects of sensorineural hearing loss and iron deficiency anemia in JLNS cases." (PMID 37568094, 2023).
lung adenocarcinoma (3 papers, 2020 to 2022). A carcinoma that arises from the lung and is characterized by the presence of malignant glandular epithelial cells. "We noted that KCNQ1 was implicated in disease items “metastasis”, “breast adenocarcinoma”, and “lung adenocarcinoma”, aside from its previously recognized role in LQTS." (PMID 35216393, 2022). "In light of this, we further examined the associations between KCNQ1 and tumors and revealed some cancer types, including breast adenocarcinoma, endometrial cancer, lung adenocarcinoma, cutaneous melanoma, and glioblastoma multiforme." (PMID 35216393, 2022). "We further used a siRNA-based approach to confirm the role of KCNQ1 in an A549 human lung adenocarcinoma epithelial cell line." (PMID 35216393, 2022). "For lung adenocarcinoma, we found that the expression levels of three genes, GPR15, HDGF, and AHHR, were associated with increased smoking-related mutational signature, while an inverse association was observed for the other four genes, NWD1, KCNQ1, CAPN8 and RPS6KA1." (PMID 32928150, 2020).
lung carcinoma (3 papers, 2013 to 2022). "Frequent allele loss in lung cancer observed in our study within the long arm of chromosome 11 (11p), especially in the 11p15.5 region where KCNQ1 is mapped—are similar to the results of others." (PMID 24091944, 2013). "Similar to our study, we noted that KCNQ1 knockdown increased the migration ability of lung cancer cells." (PMID 35216393, 2022). "In human lung cancer cells, KCNQ1 acts to regulate basal cAMP-stimulated Cl− secretion through the cystic fibrosis transmembrane conductance regulator (CFTR)." (PMID 35216393, 2022). "The transfection of si-KCNQ1OT1 can effectively knock down the expression of KCNQ1OT1, increasing KCNQ1 levels and, thus, inhibiting the malignancy and chemoresistance of lung cancer cells to paclitaxel." (PMID 32850327, 2020). "Of note, the present study unveiled that lapatinib may be a potential therapeutic drug for the treatment of lung cancer when KCNQ1 expression levels are low." (PMID 35216393, 2022). "siRNA-knockdown of KCNQ1 promoted the migration ability of lung cancer cells." (PMID 35216393, 2022). "The drug sensitivity of lapatinib showed a negative correlation with KCNQ1 expression in 100 lung cancer cell lines (r = −0.272, p value = 0.006) as well as 464 pan-cancer cell lines (r = −0.187, p value < 0.001)." (PMID 35216393, 2022). "Additionally, the KCNQ1 Opposite Strand/Antisense Transcript 1 (KCNQ1OT1) gene is a lncRNA, which has been reported to be highly expressed in colorectal and lung cancers." (PMID 32850327, 2020).
male infertility (3 papers, 2016 to 2022). The inability of the male to effect fertilization of an ovum after a specified period of unprotected intercourse. "A hypermethylation of KCNQ1 is associated with poor semen parameters or male infertility." (PMID 35163587, 2022). "KCNQ1 has also been reported in association with poor semen parameters or male infertility." (PMID 26938548, 2016).
metabolic syndrome (3 papers, 2011 to 2020). A cluster of metabolic risk factors for CARDIOVASCULAR DISEASES and TYPE 2 DIABETES MELLITUS. "This study aims to find a predictable single nucleotide polymorphism (SNP) to predict the risk of metabolic syndrome (MetS) through investigating the association of SNP in KCNQ1 gene with MetS in Han Chinese women of northern urban area." (PMID 30157802, 2018).
pituitary hormone deficiency (3 papers, 2017 to 2022). "Taken together, our results demonstrate that two missense mutations in KCNQ1 cause pituitary hormone deficiency and maternally inherited GF in humans." (PMID 29097701, 2017). "Thus, by strongly increasing the constitutive K+ conductance, the KCNQ1 variants R116L and P369L likely impair excitation-coupled hormone secretion and cause pituitary hormone deficiency in the affected individuals." (PMID 36077086, 2022). "Although the exact mechanism by which the two KCNQ1 mutations cause pituitary hormone deficiency in humans is unclear, our data suggest that the KCNQ1–KCNE2 complex may play a role in it." (PMID 29097701, 2017).
sensorineural hearing loss (3 papers, 2017 to 2022). "Apart from the autosomal dominant LQTS type 1, pathogenic variants in the gene coding for the voltage-gated potassium channel KCNQ1 are associated with additional autosomal recessive inherited congenital sensorineural hearing loss, named Jervell and Lange-Nielsen syndrome." (PMID 36498454, 2022). "Bi‐allelic mutations in the KCNQ1 gene are causal to Jervell and Lange‐Nielsen syndrome (JLNS), characterized by severe and early‐onset arrhythmias with prolonged QTc interval on surface ECG and sensorineural deafness." (PMID 28944242, 2017).
Tinnitus (3 papers, 2011 to 2015). Tinnitus is an auditory perception that can be described as the experience of sound, in the ear or in the head, in the absence of external acoustic stimulation. "It is highly likely that a mutation in KCNE3 alone may not be indicative of tinnitus, but when mutations are present in both KCNE3 and the channel with which it is interacting (e.g. KCNQ1) the biophysical properties of the channel complex are significantly altered." (PMID 21899751, 2011).
virus infection (3 papers, 2014 to 2025). "We chose these genes because of their roles in viral infection (STAT2), cardiovascular function (KCNQ1) or being the most widely used genomic locus for transgene integration (PPP1R12C)." (PMID 25299451, 2014).
Abdominal obesity (2 papers, 2015 to 2019). Excessive fat around the stomach and abdomen. "The reported T2D risk alleles of three SNPs, including the T allele of rs243021 near BCL11A, the G allele of the intronic rs10830963 in MTNR1B, and the C allele of the intronic rs2237895 in KCNQ1, contributed to a decreased risk for abdominal obesity in T2D patients." (PMID 26599349, 2015). "In CTRF+ individuals, mRNA levels of TSPAN8 associated with T2D family history (p < 0.01), of IGF2BP2 tv7 with serum glucose levels, while in the total group of controls, KCNQ1 tv1 levels reversely with BMI, central obesity, glucose and LDL (mg/dl) levels (p < 0.05)." (PMID 30728419, 2019).
acute lung injury (2 papers, 2024 to 2025). A condition of lung damage that is characterized by bilateral pulmonary infiltrates (pulmonary edema) rich in neutrophils, and in the absence of clinical heart failure. "The aim of our study was to investigate the role of the KCNQ1 pore-forming subunit of KvLQT1 channels in the outcome of ARDS parameters in a model of acute lung injury (ALI)." (PMID 38444763, 2024).
alcohol dependence (2 papers, 2022 to 2024). Physical and psychological dependence on alcohol. "For instance, KCNQ1, a gene encoding a potassium ion channel, was identified in a GWAS of alcohol dependence." (PMID 38633406, 2024).
atherosclerosis (2 papers, 2020 to 2022). A disease characterized by the build-up of fatty material and calcium deposition in the arterial wall resulting in partial or complete occlusion of the arterial lumen. "Animal experiment has confirmed that an imprinted antisense IncRNA in the KCNQ1 gene promotes macrophage lipid accumulation and accelerates the development of atherosclerosis through the miR-452-3p/HDAC3/ABCA1 pathway." (PMID 36539828, 2022).
cystic fibrosis (2 papers, 2018 to 2025). Autosomal recessive disorder caused by pathogenic variants in the CFTR gene (cystic fibrosis transmembrane conductance regulator), which encodes a chloride and bicarbonate channel expressed in epithelial cells, and follow the diagnosis criteria. "In epithelial cells, KCNE3 regulates the function of the KCNQ1 potassium ion (K+) channel in a physiologically critical cellular transport process in several organs and whose malfunction causes diseases such as cystic fibrosis, cholera, and pulmonary edema." (PMID 29607317, 2018).
endometrial cancer (2 papers, 2022 to 2024). Primary or metastatic malignant neoplasm involving the endometrium (mucous membrane that lines the endometrial cavity). "Recently, it is interesting to find that succinate can either by synergistically activated with estrogen,or through downregulating voltage-gated potassium channel subfamily Q member 1 (KCNQ1) levels to promote the growth of endometrial cancer cells in vitro and in vivo." (PMID 38291428, 2024).
gastric adenocarcinoma (2 papers, 2010 to 2023). "The lack of KCNE2-KCNQ1 co-localization was even more profound in human gastric adenocarcinoma, which again retained co-localization of KCNQ1 and HKA β." (PMID 20625512, 2010). "Comparing the transcriptomes of isolated Prom1+ gastric stem cells and their Prom1− daughter cells from normal gastric mucosa and gastric adenocarcinomas, we observe that KCNQ1 is down-regulated and KCNQ2/3/5 genes are significantly up-regulated (Q < 0.05) in gastric adenocarcinomas in this model." (PMID 37748809, 2023).
insulinoma (2 papers, 2017 to 2020). "Conversely, the significantly opposite methylation and expression changes exemplified by LSP1, H19, TH, KCNQ1, SLC22A18, OSBPL5 are thus more likely random and unrelated to insulinoma pathogenesis." (PMID 33060578, 2020).
Myocardial fibrosis (2 papers, 2023 to 2025). "While myocardial fibrosis and chronic ischemia are key modulators of KCNQ1 polymorphism's arrhythmogenic effects in ischemic cardiomyopathy, inflammatory processes or genetic mutations may play a more dominant role in NICM." (PMID 40365780, 2025).
osteosarcoma (2 papers, 2020 to 2022). A usually aggressive malignant bone-forming mesenchymal neoplasm, predominantly affecting adolescents and young adults. "Besides that, KCNQ1OT1 was shown to regulate the osteosarcoma cell behaviors and its response to cisplatin via regulating Kcnq1/DNA methyltransferase 1 mediated KCNQ1 expression." (PMID 31909901, 2020).
pancreatic cancer (2 papers, 2022 to 2024). "As KCNQ1 variants have been shown to have an association with pancreatic cancer risk, we then examined its impact on the progression of LUAD by accessing the cBioPortal web server." (PMID 35216393, 2022).
preeclampsia (2 papers, 2023 to 2024). Preeclampsia is a hypertensive disorder of pregnancy that is characterized by new-onset hypertension with proteinuria presenting after 20 weeks of gestation, and depending on mild or severe forms may initially present with severe headache, visual disturbances, and hyperreflexia. "To investigate the association between the KCNQ1 gene SNPs and preeclampsia, we analyzed the haplotypes of the KCNQ1 gene and found a linkage disequilibrium (r2 = 0.196; D′ = 0.8833)." (PMID 39465874, 2024). "In this study, we first reported that the KCNQ1 gene SNP rs231840 became associated with preeclampsia by influencing the blood glucose levels." (PMID 39465874, 2024). "Haplotype frequency and association with RBG in preeclampsia for KCNQ1 (n = 248)." (PMID 39465874, 2024). "The KCNQ1 gene SNP rs231840 might be associated with preeclampsia potentially, and this hypothesis could be tested through binary logistic regression analysis." (PMID 39465874, 2024). "Haplotype frequency and association with preeclampsia for KCNQ1." (PMID 39465874, 2024). "The KCNQ1 (TT) genotype seems to be associated with preeclampsia and might affect the regulation of blood glucose in Chinese pregnant women." (PMID 39465874, 2024). "KCNQ1 gene polymorphisms are associated with preeclampsia and might affect the regulation of blood glucose levels in Chinese pregnant women." (PMID 39465874, 2024). "We speculated that the polymorphism of the KCNQ1 gene was an essential hereditary parameter influencing the pathology of preeclampsia by regulating the level of the blood glucose." (PMID 39465874, 2024).
renal cell carcinoma (2 papers, 2022 to 2024). "It was reported that the development and metastasis of renal cell carcinoma were promoted by the miR-140-5p/KLF9/KCNQ1 axis, revealing a novel pathogenic mechanism underlying renal cell carcinoma." (PMID 38807370, 2024).
Wilms tumor (2 papers, 2021). An embryonal neoplasm characterized by the presence of epithelial, mesenchymal, and blastema components. "KCNQ1DN, which imprinted and mapped between CDKN1C and KCNQ1 on chromosome 11p15.5, is usually associated with Wilms' tumor." (PMID 33835050, 2021).
arrhythmogenic right ventricular dysplasia type 5 (1 paper, 2023). "In our study, TTN DCM type 1G, KCNQ1 LQTS type 1, MYBPC3 HCM type 4, and TMEM43 arrhythmogenic right ventricular dysplasia type 5 were the most frequent CVD, and MSH6 Lynch syndrome and PALB2 HBC were the most frequent CPC among ACMG SFs." (PMID 36635046, 2023).
ascending aortic dilatation (1 paper, 2022). "One (1.9%) developed asymmetric hypertrophy (HCM), mild mitral valve prolapse (MVP) and mild ascending aortic dilatation; additional genetic tests identified a variant of unknown significance in TPM1 and KCNQ1 genes." (PMID 35757141, 2022).
asthenospermia (1 paper, 2022). "We assessed the DNA methylation patterns of the selected gene regions using the MethylTarget technique, and detected 323 CpG sites, of which only 6 (2 in IGF-2, 1 in KCNQ1, and 3 in MEST) were significantly different between the mild asthenospermia and normozoospermia groups." (PMID 36357889, 2022).
asthma (1 paper, 2024). "Modulation of ENaC, CFTR, CaCC, KCNQ1 and KCNN4 ion channels by estrogen negatively affect airway surface liquid height and mucociliary clearance which impact on mucus production, bacterial virulence and airway inflammation, contributing to CF and asthma pathophysiology." (PMID 39026347, 2024).
atrial septal defect (1 paper, 2022). Interauricular communication is a congenital malformation characterized by a communication between the atrial chambers of the heart. "KCNQ1 is rarely associated with cardiac structural defects, although this patient presented with atrial septal defect." (PMID 36143288, 2022).
benign adenoma (1 paper, 2023). "In benign adenoma tissue, there are an up-regulation of KCNQ3 and a slight decrease in KCNQ1." (PMID 37748809, 2023).
colorectal adenocarcinoma (1 paper, 2023). The most common type of colorectal carcinoma. "We also find that most alterations in KCNQ1, a gene already implicated as a tumour suppressor in colorectal adenocarcinomas, are deletions or missense/truncating mutation events, indicating that this proposed role may extend beyond the colorectal tract." (PMID 37748809, 2023).
desmoid fibromatosis (1 paper, 2024). "This suggests a potential mechanistic link between the biallelic loss of KCNQ1 and desmoid fibromatosis in this case." (PMID 39594770, 2024). "In this study, the second hit approach suggested ATM and POLG as new candidates for association with sarcoma and identified a potential association between KCNQ1 and desmoid fibromatosis." (PMID 39594770, 2024). "There is evidence that KCNQ1 is involved in the regulation of the Wnt/b-catenin signaling pathway, which is normally upregulated and serves as the primary driver of desmoid fibromatosis." (PMID 39594770, 2024). "There are no reports of KCNQ1 involvement in desmoid fibromatosis, and our patient’s tumor harbored the well-characterized CTNNB1 somatic activating variant." (PMID 39594770, 2024).
endothelial dysfunction (1 paper, 2022). In vascular diseases, endothelial dysfunction is a systemic pathological state of the endothelium (the inner lining of blood vessels) and can be broadly defined as an imbalance between vasodilating and vasoconstricting substances produced by (or acting on) the endothelium. "A cohort study in Japan has reported that SNPs at KCNQ1 were significantly associated with coronary epicardial endothelial dysfunction." (PMID 36539828, 2022).
esophageal squamous cell carcinoma (1 paper, 2023). Esophageal squamous cell carcinoma (ESCC) is a type of esophageal carcinoma (EC) that can affect any part of the esophagus, but is usually located in the upper or middle third. "In esophageal squamous cell carcinoma (ESCC), miR-483e5p overexpression silences KCNQ1 promoting cell proliferation, migration, and invasion." (PMID 37408210, 2023).
female infertility (1 paper, 2022). Diminished or absent ability of a female to achieve conception. "Mutations in the gene that encodes the KCNQ1 K + potassium channel are associated with female infertility." (PMID 36101387, 2022).
fibromatosis (1 paper, 2024). A poorly circumscribed neoplasm arising from the soft tissues. "Of these, second hits in the tumors were identified in two patients, harboring germline variants in the KCNQ1 and POLG genes and diagnosed with fibromatosis and GIST, respectively." (PMID 39594770, 2024).
gingival overgrowth (1 paper, 2022). Excessive growth of the gingiva either by an increase in the size of the constituent cells (gingival hypertrophy) or by an increase in their number (gingival hyperplasia). "We aimed to discover the genetic defect in a single individual and three family members with gingival overgrowth and identified the KCNQ1 variants P369L and V185M, respectively." (PMID 36077086, 2022).
gingival tumor (1 paper, 2023). "In gingival tissue biopsy, we found that the mRNA expression level of KCNQ1, PIK3CA, and PIK3CB in the gingival tumor tissue of the proband was significantly increased." (PMID 37752101, 2023).
gonadoblastoma (1 paper, 2011). A mixed germ cell/sex cord-stromal tumor characterized by the presence of large germ cells which resemble seminoma cells and small cells which resemble Sertoli or granulosa cells. "The cancer risk in KCNQ1 deletion cases of BWS is presently unknown due to the low number of affected individuals however BWS patients with isolated loss of methylation within IC2 are at risk for hepatoblastoma and other tumours including rhabdomyosarcoma, gonadoblastoma and thyroid carcinoma." (PMID 22205991, 2011).
Impaired glucose tolerance (1 paper, 2018). An abnormal resistance to glucose, i.e., a reduction in the ability to maintain glucose levels in the blood stream within normal limits following oral or intravenous administration of glucose. "Of similar interest, Plagl1 or Kcnq1 dysregulation are responsible for impaired glucose tolerance associated with insulin secretion defects." (PMID 30443025, 2018).
infantile epileptic encephalopathy (1 paper, 2021). an epileptic condition characterized by epileptiform abnormalities associated with progressive cerebral dysfunction. "In this regard, we noted that one of the neuronal paralogs of KCNQ1, KCNQ2, is known to be subject to GOF mutations that cause a severe disease, early infantile epileptic encephalopathy." (PMID 33600800, 2021).
infertile (1 paper, 2022). "KCNQ1 and IGF-2 have also been documented to be associated with serious sperm DNA damage in infertile males." (PMID 36357889, 2022).
intrauterine growth restriction (1 paper, 2018). "Although impaired potassium channel function has been proposed to cause intrauterine growth restriction, loss-of-function mutations in KCNQ1 may not account for this phenotype." (PMID 29740400, 2018).